DSCAM-AS1 (DSCAM antisense RNA 1)
Synonyms: M41
Gene: Long non-coding RNA gene on chromosome 21 (40,383,029 to 40,385,439, forward strand). Ensembl gene ENSG00000235123.
Diseases named in the same sentence as DSCAM-AS1 in open-access papers:
DSCAM-AS1 is named in the same sentence as 23 diseases in open-access papers, as found by Europe PMC text mining. Sharing a sentence is not in itself a finding about the gene and the disease. The quoted sentences say what the papers report.
breast carcinoma (24 papers, 2016 to 2024). "Annotated lncRNAs already implicated in breast cancer (DSCAM-AS1, NEAT1, SNHG3, ZFAS1) also had a significant (FDR ≤ 0.3) effect, indicating the screen was able to identify functional lncRNAs." (PMID 38745269, 2024). "Of note, DSCAM-AS1 has been implicated in conferring resistance to tamoxifen in breast cancer." (PMID 37395734, 2023). "We identified downregulation of a lncRNA, Down syndrome cell adhesion molecule antisense RNA 1, DSCAM-AS1, upon progesterone treatment in breast cancer cells." (PMID 37395734, 2023). "Second, the findings suggest that DSCAM-AS1 functions as a miRNA sponge to help maintain the high expression of ER in breast cancer cells." (PMID 36578092, 2022). "Mechanistically, the oncogenic action of DSCAM-AS1 was demonstrated to interact with nuclear ribonucleoprotein hnRNPL in breast cancer cells, which has been found to facilitate progression of breast cancer and induce resistance to tamoxifen." (PMID 35885035, 2022). "We identified a significant downregulation in the expression of a long non-coding RNA, Down syndrome cell adhesion molecule antisense DSCAM-AS1, in response to progesterone treatment in breast cancer." (PMID 36578092, 2022). "Progesterone downregulates the expression of DSCAM-AS1 specifically in PR-positive breast cancer cells, wherein PR modulates the genomic binding pattern of ER, the classical activator of DSCAM-AS1, in response to progesterone." (PMID 36578092, 2022). "We further show that knockdown of DSCAM-AS1 mimics the effect of progesterone in impeding cell migration and invasion in PR-positive breast cancer cells, while its overexpression shows an opposite effect." (PMID 36578092, 2022). "For instance, DSCAM-AS1 up-regulation can increase Tamoxifen resistance in breast cancer through sequestering miR-137, then increasing expression of EPS8." (PMID 34708048, 2021). "DSCAM-AS1 silencing in breast cancer cells has led to alteration of more than 900 genes which have been mostly related with regulation of cell cycle and immune responses." (PMID 34708048, 2021). "DSCAM-AS1 is upregulated in breast cancer tissues and in tamoxifen resistant cells and positively associated with high grade and metastasis." (PMID 34359587, 2021). "Since the expression of DSCAM-AS1 was dramatically elevated in many breast cancer and lung adenocarcinoma patients, we then investigated the clinical relevance of the altered expressions of DSCAM-AS1." (PMID 32929382, 2020). "Significant growth inhibition was observed in breast cancer and lung adenocarcinoma cells after knockout of DSCAM-AS1." (PMID 32929382, 2020). "Luminal A types showed overexpression of LINC00160, and abundance of DSCAM‐AS1 was reported in luminal B subtypes of breast cancer." (PMID 30959550, 2019). "DSCAM-AS1 knockdown reduced the proliferative ability of breast cancer cell lines while DSCAM-AS1 overexpression enhanced proliferation of ER+ breast cancer cell lines." (PMID 29719633, 2018). "Next, we knocked down DSCAM‐AS1 using 2 siRNAs in 2 luminal breast cancer cell lines, MCF‐7 and T‐47D." (PMID 30430768, 2018). "In the current study, we aimed to reveal the role of DSCAM‐AS1 in luminal breast cancer progression and prognosis by utilizing cellular experiments and analyzing a large cohort of luminal breast cancer samples." (PMID 30430768, 2018). "DSCAM-AS1 mediates tumour progression and tamoxifen resistance in breast cancer through interacting protein hnRNPL." (PMID 29757368, 2018). "The unique attributes that lies in DSCAM-AS1 such as its high expression, tissue of origin specificity, and breast tumour phenotype specificity make it an important biomarker of luminal breast cancer." (PMID 29732012, 2018). "This is suggestive of a function of DSCAM-AS1 downstream ERα that is probably limited to breast carcinoma development." (PMID 26621851, 2016).
breast carcinoma (continued). "Moreover, the overexpression of DSCAM-AS1 in tamoxifen-resistant cell line models, which also overexpress ESR1, highlights the potential role of DSCAM-AS1 in endocrine therapy resistance in breast cancer." (PMID 37395734, 2023). "Another study found down syndrome cell adhesion molecule antisense RNA 1 (DSCAM-AS1) increases QPRT expression in breast cancer cells via competitively binding miRNA-150-5p and miRNA-2467-3p, resulting in increased cell growth, migration, and invasion of estrogen-receptor breast cancer cells." (PMID 37876966, 2023). "Interestingly, the analyses identified DSCAM-AS1 as a novel target of progesterone in breast cancer." (PMID 36578092, 2022). "Overexpression of DSCAM-AS1 promotes the cell proliferation of the luminal breast cancer cell line." (PMID 35692369, 2022). "Additionally, DSCAM-AS1 sponges the activity of miR-130a that regulates the expression of ESR1 by binding to its 3’-UTR to mediate the effect of progesterone in breast cancer cells." (PMID 36578092, 2022). "In xenograft model of breast cancer, DSCAM-AS1 silencing could decrease the tumorigenic potential of cancer cells and increase miR-204-5p levels." (PMID 34708048, 2021). "The pathogenic roles of DSCAM-AS1 have been vastly assessed in breast cancer, yet its roles are not restricted to this type of cancer." (PMID 34708048, 2021). "Thus, DSCAM-AS1 has been suggested as a possible target for enhancement of survival of this kind of breast cancer." (PMID 34708048, 2021). "Although the manner in which DSCAM-AS1 functions in breast cancers remains unclear, the RNA-binding protein heterogeneous nuclear ribonucleoprotein L (hnRNPL) is required for DSCAM-AS1 activity in MCF7 and T47D cells." (PMID 32486413, 2020). "DSCAM‐AS1 is a prognostic factor in patients with luminal breast cancer." (PMID 30430768, 2018). "We also determined the distribution of DSCAM‐AS1 in different breast cancer subtypes." (PMID 30430768, 2018). "Interestingly, DSCAM-AS1 is an antisense intronic lncRNA that is highly specific for luminal breast cancer." (PMID 29732012, 2018). "Furthermore, knockdown of DSCAM-AS1 in these tamoxifen-resistant cells reduced the proliferation rate to the level of parental MCF7 cells, suggesting a role of DSCAM-AS1 in tumor progression and tamoxifen resistance in ER+ breast cancer." (PMID 29719633, 2018). "Indeed, DSCAM-AS1 is a cancer specific lncRNA that is highly expressed in ER+ cells, and is involved in the proliferation of luminal breast cancer cell lines." (PMID 29719633, 2018). "This approach nominated DSCAM-AS1 as a lncRNA expressed at a very high level in breast cancer tissues, containing ER promoter binding, and exhibiting the strongest oestrogen induction in MCF7 and T47D cells by both RNA-seq and quantitative PCR (qPCR) validation." (PMID 27666543, 2016). "Moreover, DSCAM-AS1 deletion can extensively mimic the effect of deleting ERα in breast cancer cells." (PMID 26621851, 2016). "The proximal AERBS that overlaps the DSCAM-AS1 promoter may be involved in the regulation of DSCAM-AS1 transcription in ER+ breast cancer cells, as also suggested by our reporter assays." (PMID 26621851, 2016). "Furthermore, in breast cancer cells, transcription of DSCAM-AS1 was shown to be mainly activated by FOXA1 and was in turn able to affect expression of its regulators ERα and FOXA1 via interaction with YBX1, forming a positive feedback loop leading to breast cancer progression." (PMID 35885035, 2022). "Interestingly, DSCAM-AS1 knockdown could mimic the effect of progesterone by inhibiting breast cancer cell migration and invasion comparable to the extent obtained following treatment of the PR-positive T47-D and BT474 cells with progesterone." (PMID 36578092, 2022).
breast carcinoma (continued). "Moreover, increased expression of DSCAM-AS1 was associated with a worse overall survival in breast cancer patients according to our in silico analysis, and knockdown of DSCAM-AS1 inhibited breast cancer cell proliferation, increased apoptosis and inhibited cell cycle progression in this study." (PMID 28738804, 2017). "DSCAM-AS1 functions as a microRNA sponge for miR-130a, which is similarly sponged by DSCAM-AS1, targets the 3′-UTR of ESR1 that is a crucial regulator of breast cancer progression and metastasis." (PMID 37395734, 2023). "Progesterone downregulates the expression of DSCAM-AS1, a known ncRNA member of the ER signaling pathway, and increases the expression of miR-130a that inhibits ESR1, to suppress breast cancer cell invasion and migration." (PMID 36578092, 2022). "To further demonstrate the impact of DSCAM-AS1 on aggressive cancer phenotypes, we overexpressed DSCAM-AS1 in T47D and ZR75-1, two ER-positive breast cancer cell lines with moderate DSCAM-AS1 expression, and observed an increase in the invasion phenotype." (PMID 27666543, 2016). "Moreover, DSCAM-AS1 expression is elevated in tamoxifen-resistant breast cancer tissues, and the knockdown and overexpression experiments of DSCAM-AS1 in breast cancer cell lines, such as MCF7 and T47D, suggest that DSCAM-AS1 promotes tamoxifen resistance." (PMID 32486413, 2020). "Surprisingly, no significant copy number amplification was observed in neither breast cancer nor lung adenocarcinoma, indicating CNVs are not the reason for overexpression of DSCAM-AS1." (PMID 32929382, 2020). "Moreover, DSCAM-AS1 expression is higher in luminal and HER2-positive breast cancers, and particularly in the luminal B subtype." (PMID 32486413, 2020). "They found that DSCAM‐AS1 was a major discriminant of the luminal subtype (ER+) of breast cancer and is not expressed in basal‐like breast cancer." (PMID 30430768, 2018). "DSCAM‐AS1 was highly expressed in luminal and Her‐2 overexpression breast cancers but not in TNBC, indicating that it plays important roles in ER+ breast tumors." (PMID 30430768, 2018). "If ERα is also regulated by DSCAM‐AS1, they may form a positive feedback, which means ERα and DSCAM‐AS1 can maintain their high expression each other in luminal (ER+) breast cancer." (PMID 30430768, 2018). "First, DSCAM-AS1 was previously reported to be regulated by ERα 22, 23, 62, 63, and FOXA1 and ERα usually bind together to regulate their target genes in breast cancer, so the dominant expression of DSCAM-AS1 in ER+ breast cancer may be caused by cooperative regulation of FOXA1 and ERα." (PMID 32929382, 2020). "To further verify the regulation roles of FOXA1 on DSCAM-AS1, we knocked down FOXA1 by siRNAs in lung adenocarcinoma, breast cancer, and prostate cancer cell lines, respectively, qPCR and Western blotting showed these siRNAs could effectively silence FOXA1 levels." (PMID 32929382, 2020).
cervical cancer (4 papers, 2020 to 2023). A primary or metastatic malignant neoplasm involving the cervix. "In cervical cancer, miR-877-5p acts as a downstream target of long non-coding RNA DSCAM-AS1, and DSCAM-AS1 plays a vital role in the tumorigenesis via miR-877-5p/ATXN7L3 axis in cervical cancer." (PMID 34124974, 2021). "In cervical cancer cells, DSCAM-AS1 interacts with miR-877-5p to increase expression of its target gene ATXN7L3." (PMID 34708048, 2021). "Independent studies in non-small cell lung cancer, colorectal cancer, osteosarcoma, hepatocellular carcinoma, melanoma and cervical cancer have validated participation of DSCAM-AS1 in the carcinogenic processes." (PMID 34708048, 2021).
lung carcinoma (4 papers, 2018 to 2025). "Expression of DSCAM-AS1 has been reported to be up-regulated in lung cancer tissues compared with normal samples." (PMID 34708048, 2021). "We analyzed the expression patterns between FOXA1 and DSCAM-AS1 using TCGA breast and lung cancer datasets." (PMID 32929382, 2020). "Intriguingly, in lung cancer, DSCAM-AS1 showed distinctive expression in LUAD but was almost undetectable in LUSC." (PMID 32929382, 2020). "Another study in lung cancer has verified up-regulation of DSCAM-As1 in tumor samples and assessed the overall survival of these patients following surgery through Kaplan–Meier survival analysis showing correlation between DSCAM-AS1 up-regulation and poor overall survival of patients." (PMID 34708048, 2021).
breast tumor (2 papers, 2018 to 2021). "DSCAM Antisense RNA 1 (DSCAM−AS1) is an example of this group of transcripts which has been firstly identified in an attempt to find differentially expressed transcripts between breast tumor cells and benign breast samples." (PMID 34708048, 2021).
liver cancer (2 papers, 2021 to 2024). An epithelial or non-epithelial malignant neoplasm that arises from the liver. "The importance of DSCAM-AS1 up-regulation in deterioration of patients’ outcome has been validated in independent studies in breast, lung, colorectal, skin, bone and liver cancers potentiating this lncRNA as a prognostic marker." (PMID 34708048, 2021).
prostate carcinoma (2 papers, 2020 to 2024). A carcinoma that arises from epithelial cells of the prostate gland. "DSCAM-AS1 is up-regulated in prostate cancer and regulates the progression of prostate cancer cells by targeting miR-338-3p." (PMID 38605206, 2024). "DSCAM-AS1 was significantly upregulated in prostate cancer tissues and cells compared with normal tissues and cells." (PMID 38605206, 2024). "The cell migration and invasion of prostate cancer were also decreased by DSCAM-AS1 knockdown, and the inhibitory effect was also reversed by transfection with the miR-338-3p inhibitor." (PMID 38605206, 2024). "It was found that DSCAM-AS1 upregulation could serve as a warning of deterioration and poor prognosis in prostate cancer patients, and that knockdown of DSCAM-AS1 expression inhibited the progression of prostate cancer cells." (PMID 38605206, 2024). "The higher the expression level of DSCAM-AS1, the lower the 5-year survival rate and the worse the prognosis In addition, DSCAM-AS1, AJCC stage, differentiation, lymph node metastasis, and PSA all have potential as prognostic markers for prostate cancer patients." (PMID 38605206, 2024).
colorectal cancer (1 paper, 2021). A primary or metastatic malignant neoplasm that affects the colon or rectum. "Suppression of DSCAM-AS1 expression in colorectal cancer cells has resulted in down-regulation of Notch-1." (PMID 34708048, 2021).
endometrial cancer (1 paper, 2022). Primary or metastatic malignant neoplasm involving the endometrium (mucous membrane that lines the endometrial cavity). "Our data suggest downregulation of WNT7a by DSCAM-AS1, which is overexpressed in endometrial cancer, so this interaction might contribute to endometrial carcinogenesis." (PMID 35885035, 2022). "As we observed both DSCAM-AS1 to be overexpressed in endometrial cancer tissue and growth inhibition of HEC-1B cells after its knockdown, we now examined transcriptome alterations and signaling pathways which might underlie these observations." (PMID 35885035, 2022). "Finally, we tested whether the genes being regulated after DSCAM-AS1 knockdown would be correlated with this lncRNA in endometrial cancer tissue." (PMID 35885035, 2022).
endometrial tumor (1 paper, 2022). "Our analyses demonstrating elevated expression of DSCAM-AS1 in endometrial tumor tissue are in line with studies reporting increased DSCAM-AS1 levels in several cancer types." (PMID 35885035, 2022).
gastric cancer (1 paper, 2021). A primary or metastatic malignant neoplasm involving the stomach. "Similarly, lncRNAs DSCAM-AS1, LINC00467, and SNHG17 have been reported to promote breast, lung, and gastric cancer, respectively, highlighting the efficacy of our screen to identify dysregulated lncRNAs." (PMID 34302808, 2021).
lung adenocarcinoma (1 paper, 2020). A carcinoma that arises from the lung and is characterized by the presence of malignant glandular epithelial cells. "Further research is needed to explore the cooperative transcriptional factor mediates distinctively expressed of DSCAM-AS1 in lung adenocarcinoma." (PMID 32929382, 2020). "Silencing ERα also resulted in no significant change of DSCAM-AS1 in lung adenocarcinoma." (PMID 32929382, 2020).